AXIN1 (axin 1)
Description:
Component of the beta-catenin destruction complex required for regulating CTNNB1 levels through phosphorylation and ubiquitination, and modulating Wnt-signaling. Controls dorsoventral patterning via two opposing effects; down-regulates CTNNB1 to inhibit the Wnt signaling pathway and ventralize embryos, but also dorsalizes embryos by activating a Wnt-independent JNK signaling pathway. In Wnt signaling, probably facilitates the phosphorylation of CTNNB1 and APC by GSK3B. Enhances TGF-beta signaling by recruiting the RNF111 E3 ubiquitin ligase and promoting the degradation of inhibitory SMAD7. Activates the AMP-activated protein kinase (AMPK) in response to calorie restriction by acting as a molecular adapter: recruited to late endosome membrane by the V-ATPase complex downstream of TULP3, and mediates association between STK11 and its AMPK substrates PRKAA1 and/or PRKAA2, leading to AMPK activation (By similarity).
Synonyms: AXIN; PPP1R49; CMDOH
Tractability: Small molecule: a structure with a bound ligand is known. Antibody: UniProt places it where antibodies can reach, with medium confidence; its Gene Ontology location is reachable by antibodies, with medium confidence. PROTAC: UniProt records ubiquitination sites on it; ubiquitination databases record sites on it.
Chemical probes: HLY78
Gene: Protein-coding gene on chromosome 16 (287,440 to 352,730, reverse strand). Ensembl gene ENSG00000103126.
Subcellular location: Cytoplasm; Nucleus; Membrane; Cell membrane; Late endosome
Subcellular location (Human Protein Atlas): Nucleoplasm; Primary cilium; Vesicles; Nucleoli; Primary cilium tip; Primary cilium transition zone
Pathways (Reactome):
Disease: APC truncation mutants have impaired AXIN binding; AXIN missense mutants destabilize the destruction complex; CTNNB1 S33 mutants aren't phosphorylated; CTNNB1 S37 mutants aren't phosphorylated; CTNNB1 S45 mutants aren't phosphorylated; CTNNB1 T41 mutants aren't phosphorylated; Deletions in the AXIN1 gene destabilize the destruction complex; Signaling by GSK3beta mutants; Truncations of AMER1 destabilize the destruction complex
Signal Transduction: Beta-catenin phosphorylation cascade; Degradation of AXIN; Degradation of beta-catenin by the destruction complex; Disassembly of the destruction complex and recruitment of AXIN to the membrane; Estrogen-dependent gene expression; TCF dependent signaling in response to WNT
Gene expression (Transcription): RUNX1 regulates estrogen receptor mediated transcription; RUNX1 regulates transcription of genes involved in WNT signaling
Metabolism of proteins: Ub-specific processing proteases
Gene Ontology:
Molecular function: beta-catenin binding; enzyme binding; I-SMAD binding; identical protein binding; molecular adaptor activity; protein binding; protein serine/threonine kinase activator activity; protein serine/threonine kinase binding; SMAD binding; ubiquitin protein ligase binding; ubiquitin-like ligase-substrate adaptor activity; armadillo repeat domain binding; protein homodimerization activity; protein kinase binding; protein-macromolecule adaptor activity; signaling adaptor activity; protein domain specific binding; R-SMAD binding
Biological process: beta-catenin destruction complex assembly; negative regulation of canonical Wnt signaling pathway; positive regulation of protein catabolic process; positive regulation of protein ubiquitination; protein-containing complex assembly; cell development; cellular response to glucose starvation; negative regulation of TORC1 signaling; positive regulation of JNK cascade; positive regulation of proteasomal ubiquitin-dependent protein catabolic process; positive regulation of ubiquitin-dependent protein catabolic process; proteasome-mediated ubiquitin-dependent protein catabolic process; negative regulation of Wnt signaling pathway
Cellular component: beta-catenin destruction complex; cell periphery; cytoplasm; lateral plasma membrane; nucleolus; nucleoplasm; nucleus; perinuclear region of cytoplasm; cytoplasmic vesicle; cytosol; late endosome; plasma membrane; cell cortex; membrane; microtubule cytoskeleton; protein-containing complex; Wnt signalosome
Genetic constraint (gnomAD): Loss-of-function variants: 31 observed, 74.34 expected, observed/expected ratio (o/e) 0.42, 90% interval 0.31 to 0.56. The upper end of that interval is the gene's LOEUF score, 0.56, which puts it in group 2 of 6, group 1 being the genes least tolerant of losing a copy. Missense variants: 1,140 observed, 1,159 expected, observed/expected ratio (o/e) 0.98, 90% interval 0.94 to 1.03. Synonymous variants: 545 observed, 486.12 expected, observed/expected ratio (o/e) 1.12, 90% interval 1.04 to 1.2.
Cancer hallmarks: cell replicative immortality (suppresses); escaping programmed cell death (suppresses); suppression of growth (promotes)
Homologues: Orthologues: macaque AXIN1 (98% identical), chimpanzee AXIN1 (93% identical), rat Axin1 (88% identical), dog AXIN1 (88% identical), mouse Axin1 (87% identical), guinea pig AXIN1 (87% identical), pig AXIN1 (83% identical), tropical clawed frog axin1 (72% identical), zebrafish axin1 (64% identical). Paralogues in human: AXIN2 (44% identical), RGS12 (14% identical), RGS14 (12% identical), RGS9 (11% identical), RGSL1 (9% identical), RGS22 (9% identical), RGS11 (8% identical), RGS6 (7% identical), RGS3 (7% identical), RGS18 (7% identical), RGS7 (6% identical), RGS16 (6% identical), and 11 more.
Diseases named in the same sentence as AXIN1 in open-access papers:
AXIN1 is named in the same sentence as 135 diseases in open-access papers, as found by Europe PMC text mining. Sharing a sentence is not in itself a finding about the gene and the disease. The quoted sentences say what the papers report.
hepatocellular carcinoma (47 papers, 2003 to 2026). A malignant tumor that arises from hepatocytes. "Clinically, patients with HBV-associated hepatocellular carcinoma (HCC) who show reduced AXIN1 expression in pericarcinoma tissues have low overall and disease-free survival rates, as well as higher HBV levels in their blood." (PMID 39384753, 2024). "Dysregulation of the Wnt/β-catenin pathway due to Axin1 mutations is associated with various cancers, especially gastrointestinal (GI) cancers, such as hepatocellular carcinoma (HCC), gastric cancer, and colorectal cancer." (PMID 38010886, 2023). "AXIN1 mutations are observed in 8-10% of hepatocellular carcinomas (HCCs) and originally were considered to support tumor growth by aberrantly enhancing β-catenin signaling." (PMID 33811251, 2021). "Given that aplykurodin A promoted oncogenic β-catenin degradation, we tested its effect on the growth of AXIN1-mutated hepatoma cells." (PMID 32294900, 2020). "Mutations in APC gene have frequently been identified in colon cancer as well, while mutations in AXIN1, the gene for Axin1, have been identified in hepatocellular carcinoma and medulloblastoma." (PMID 27590724, 2016). "AXIN1 mutations have been reported in a colon carcinoma cell line, hepatocellular carcinoma (HCC), ovarian endometrioid adenocarcinoma, and sporadic medulloblastoma." (PMID 12771989, 2003). "Additionally, genes like PDE4DIP, UBXN11, and AXIN1 are associated with hepatocellular carcinoma, and a de novo mutation in the SF3B2 gene relates to craniofacial microsomia." (PMID 40136557, 2025). "Moreover, treatment of these AXIN1-mutated hepatoma cells with aplykurodin A activated caspase-3/7, which is consistent with an increase in apoptosis." (PMID 32294900, 2020). "To reveal underlying mechanism of aplykurdoin A-mediated growth inhibition, we examined whether aplykurodin A induces apoptosis in AXIN1-mutated hepatoma cells." (PMID 32294900, 2020). "Given that aplykurodin A decreased the amount of β-catenin protein, we postulated that aplykurodin A might stimulate autophagic cell death in AXIN1-mutated hepatoma cells." (PMID 32294900, 2020). "Inactivation of the AXIN1 gene has been demonstrated to induce β-catenin/TCF transcription, and AXIN1 gene mutations have been described in hepatocellular carcinomas, hepatoblastomas, colorectal cancers, ovarian endometrioid adenocarcinomas and in sporadic medulloblastomas." (PMID 14970870, 2004). "In hepatocellular carcinoma (HCC), AXIN1 mutations associate with a poor-prognosis subtype distinct from β-catenin-mutant HCC (CTNNB1)." (PMID 41550750, 2026). "In hepatocellular carcinoma cell lines, Axin1 functional inactivation activated the Wnt/β-catenin signaling pathway." (PMID 40038789, 2025). "Tankyrase inhibitors (e.g., XAV939, IWR-1, G007-LK) have shown potential by stabilizing substrates like Axin1/2 and suppressing hyperactive Wnt/β-catenin signaling, frequently observed in colorectal cancer and hepatocellular carcinoma." (PMID 40001540, 2025). "AXIN1 deficiency activates WNT/β-catenin signaling, TGFβ signaling, and YAP/TAZ, but only inhibiting YAP/TAZ can curtail hepatocellular carcinoma resulting from AXIN1 deficiency." (PMID 38291457, 2024). "Regarding the role played by gene mutations, changes in Hbx modulate the expression of Wnt-5a in hepatoma cells, whereas inactivating mutations in APC, AXIN1 and AXIN2 genes or methylation in APC aberrantly modify the Wnt signaling response." (PMID 37512809, 2023). "Lower expression of AXIN1 has been reported in several cancerous cells like hepatocellular carcinoma." (PMID 36510340, 2023). "miR-650 is a newly identified miR, and increasing studies have demonstrated that miR-650 plays critical roles in cancer progression, such as mediating the Wnt signalling pathway/AXIN1 (axis inhibition protein 1) axis in hepatocellular carcinoma." (PMID 35331235, 2022).
hepatocellular carcinoma (continued). "This is consistent with the finding that the overexpression of AXIN1 inhibits cell growth in hepatocellular carcinoma (HCC)." (PMID 31382613, 2019). "Small-molecule-based up-regulation of C/EBP-β induces AXIN1 gene expression and down-regulates the intracellular β-catenin level, thereby inhibiting hepatoma cell growth." (PMID 30283086, 2018). "Axin1 is thought to promote apoptosis in hepatocellular carcinoma cells and cardiomyocytes." (PMID 39494352, 2024). "The activation of WNT/β-catenin signaling during hepatocellular carcinoma initiation and development may represent an additional phenomenon following the suppression of AXIN1." (PMID 38291457, 2024). "Axin1‐mutant hepatocellular carcinoma cells (HCC, also known as Alexander cells) displayed a strong enrichment in macropinosome‐like vesicles and increase in fluorescent dextran uptake, promptly blocked by EIPA or IPA‐3." (PMID 33619734, 2021). "Overexpression of Axin1 inhibits hepatocellular carcinoma (HCC) cell growth and increased expression of Axin1 by X-ray irradiation inhibits lung cancer cell proliferation and invasion." (PMID 32486158, 2020). "Among these SMGs, MACF1 (5.17%, 18/348) and AXIN1 (0.86%, 3/348, all of the three patients were with iCCA), which is commonly considered as one of the potential drivers in hepatocellular carcinoma (HCC), are two interactive components of the β-catenin/Wnt signaling pathway." (PMID 35650238, 2022). "Similarly, loss of Axin1 was found to induce hepatocellular carcinoma (HCC) in the absence of β‐catenin activation." (PMID 35000262, 2022).
colorectal cancer (35 papers, 2004 to 2026). A primary or metastatic malignant neoplasm that affects the colon or rectum. "There was a relationship between AXIN1 rs9921222 polymorphism and colorectal cancer in the Rosales‐Reynoso study." (PMID 36510340, 2023). "It had already been shown that AXIN1 was mutated in colorectal cancers and wild-type can induce apoptosis in colorectal cancer cells." (PMID 26222184, 2015). "This region bears a total of 167 known genes among which AXIN1 appears a serious candidate as it had been shown to be mutated in colorectal cancers and wild-type axin 1 can induce apoptosis in colorectal cancer cells." (PMID 24559140, 2014). "Inactivating mutations of APC gene in colorectal cancer and AXIN1 in HCC also activate canonical Wnt signaling by the same mechanism." (PMID 19849855, 2009). "Concordantly, loss of AXIN2 disrupted regulation of AXIN1 expression by TNKS in SW480 colorectal cancer cells, which may have therapeutic implications for colorectal cancer through TNKS inhibitors." (PMID 39022865, 2025). "The adenomatous polyposis coli protein was mainly altered in adenomas, and that, along with the increase in colorectal cancer of GSK3β, axin 1 and ubiquitin-mutated proteins, may prevent the phosphorylation of beta-catenin by the destroyer complex and its subsequent degradation in the proteasome." (PMID 27462886, 2016). "Here, we found that knockout or knockdown of AXIN2 in colorectal cancer cells increased the protein stability of AXIN1." (PMID 39022865, 2025). "Our mechanistic studies with transiently expressed proteins suggest that AXIN2 promotes TNKS‐mediated degradation of AXIN1 in colorectal cancer cells by increasing TNKS–AXIN1 interaction." (PMID 39022865, 2025). "In the present study, we noted that knockout or knockdown of AXIN2 in human SW480 colorectal cancer cells resulted in higher protein levels of AXIN1, which was a result of increased protein stability." (PMID 39022865, 2025). "Here, we reveal that TRIM15 interferes with the polymerization of Axin1, thereby promoting Wnt activation and colorectal cancer growth." (PMID 41461634, 2025). "For instance, inhibiting nicotinamide phosphoribosyltransferase (NAMPT) has been shown to suppress colorectal cancer cell proliferation by increasing AXIN1 expression." (PMID 38291457, 2024). "CK1ε enhanced AXIN1 degradation by the ubiquitin–proteasome pathway by promoting the interaction of E3 ubiquitin‐protein ligase SIAH1 with AXIN1 in colorectal cancer cells." (PMID 38419282, 2024). "In this study, we found that CK1δ/ε inhibitors significantly enhanced AXIN1 protein level in colorectal cancer (CRC) cells through targeting CK1ε." (PMID 38419282, 2024). "Axin1 of NTERA-2, a pluripotent human embryonic carcinoma cell with an intact canonical Wnt/β-catenin cascade and a low level of Wnt autocrine signaling, and Axin1 of HCT116, a human colorectal carcinoma cell with a β-catenin mutation, were analyzed." (PMID 35707358, 2022). "In APC-mutated colorectal cancer cells, TNKSi resulted in the accumulation of cytoplasmic puncta and β-catenin degradasomes containing TNKS1/2, AXIN1/2, APC, GSK3β, and β-catenin." (PMID 34337362, 2021). "AXIN1 is presumed to be a tumor suppressor in many types of cancers, especially colorectal cancer (CRC)." (PMID 34863211, 2021). "Among the three members APC, Axin1, GSK3β and CKIα of the destruction complex family, only Axin1 co-precipitated with 5-HT1DR in 5-HT1DR overexpression LoVo colorectal cancer cells." (PMID 26214021, 2015). "Next, we generated a xenograft tumor model using fluorescence-labeled Axin1-overexpressed colorectal cancer cell." (PMID 26214021, 2015). "Consistent with reported results on APC-mutant colorectal cancer cells, tankyrase inhibitors stabilized Axin1 expression in DU4475 breast cancer cells, that harbor a mutant APC." (PMID 23144924, 2012).